PIM1 (Pim-1 proto-oncogene, serine/threonine kinase)
Diseases named in the same sentence as PIM1 in open-access papers (continued):
Sharing a sentence is not in itself a finding about the gene and the disease.
cancer (continued). "Compelling the prospect into consideration that PIM1 plays a vital role in cell cycle progression and apoptosis where different mutations can cause complex diseases, including cancer, we envisioned exploring the impacts of mutations on PIM1 using advanced computational approaches." (PMID 34679086, 2021). "These insights may be further explored to develop therapeutic strategies against PIM1 associated diseases, including cancer." (PMID 34679086, 2021). "Moreover, with the phosphorylation on AR caused by Pim1 on serine-213 residue, cancer cells (prostate) have become more aggressive and unaffected by androgen ablation therapy." (PMID 32961987, 2020). "Pim-1 is over expressed inhuman cancer diseases and has been associated, with metastasisand overall treatment response; in experimental models, inhibitionof Pim-1 suppressed cell proliferation and migration, inducedapoptotic cell death and synergized with other chemotherapeuticagents." (PMID 31435157, 2019). "Furthermore, elevated PIM-1 expression is associated with malignant tumors and a higher tumor grade." (PMID 28938604, 2017). "We extend our hypothesis that Pim1, a kinase that has been associated with genomic instability in cancers, could also be involved in genomic instability in Cx32 mutations." (PMID 24982612, 2014). "Oncogenes are a group of mutated genes that may cause cancer, such as JunB and PIM1." (PMID 36479105, 2022). "Moreover, PIM1 has been found to be associated with drug resistance of cancer cells." (PMID 32504181, 2020). "Our data indicate that PIM-1 overexpression is observed at high frequency in CTCs from mCRPC patients and this finding, in combination with androgen receptor splice variant 7 (AR-V7) expression in CTCs, suggest its potential role as a very promising target for cancer therapy." (PMID 32397108, 2020). "In addition to PIM1, miR-33a has been also shown to directly target a variety of genes associated with cancer progression including several genes associated with cell cycle regulation such as CDK6 (cyclin-dependent kinase 6) and CCND1 (cyclin D1), which are directly targeted by miR-33a." (PMID 28947967, 2017). "Given PIM1’s role in cancer and its application as a target for anticancer drug screening, we have reason to believe that PIM1 inhibitors, as part of a combination therapy regimen, hold considerable potential, especially for immunocompromised individuals." (PMID 41557744, 2026). "In vitro studies have shown that PIM-1 overexpression enhances tumor growth and confers resistance to drug-induced apoptosis in cancer cells." (PMID 39521748, 2025). "The constitutively active serine/threonine kinases CK2 and PIM-1 show abnormally high expression levels in many cancers, particularly prostate, breast, and lung cancers, and in hematological cancers." (PMID 40565356, 2025). "In conclusion, the exclusive PTM of NuMA in cancer cells by polyADP-ribosylation and by Pim1 phosphorylation unveils a new target for the eradication of cancer cells, exploiting the dependence of the bipolar clustering of NuMA in mitotic spindles on its PTM." (PMID 40681496, 2025). "Among all overlapping cancer genes regulated by these two eccMIR clusters, the downregulated expression of PIM1, KLF4, and FBLN2 was confirmed via RT-qPCR." (PMID 39920810, 2025). "We found that the Akt–GSK3β axis can be regulated by TRAF6, which is consistent with the literature on the role of Pim1 in cancer." (PMID 40164682, 2025). "Enrichment analysis revealed KEGG pathways associated with cancer, with KRAS and PIM1 appearing as key nodes." (PMID 40512223, 2025). "Our two new likely activating variants (in PIM1 and MAP2K3) have very low sample counts in current cancer datasets." (PMID 41152984, 2025). "First, we assessed S9 phosphorylation in various cancer models (prostate, colon, renal, and lung) after overexpression of PIM1." (PMID 38097734, 2024).
cancer (continued). "Glycogen synthase kinase 3β (GSK3β) is a direct substrate of PIM1, and its tumor-suppressive effects on cancer cells are blocked by PIM1-induced phosphorylation, leading to increased cell migration and adhesion." (PMID 39227379, 2024). "Abnormal expression of PIM1 kinase in various cancers has prompted extensive research into small molecule inhibitors targeting PIM1 proteins, with several of these inhibitors advancing to clinical trials." (PMID 39227379, 2024). "This work identifies PIM1 as a key player regulating lipid profile of cancer cells both in vitro and in vivo." (PMID 38097734, 2024). "The identification of this signaling axis poises PIM1 as a critical driver of cancer cell invasion and metastasis and provides a novel target to oppose the prometastatic effect of hypoxia in PCa." (PMID 37042842, 2023). "Because PIM1 showed a prominent effect on phosphorylation of GBP1 and is a known GBP1-interactor in cancer cells, we performed additional experiments with recombinant PIM1 and GBP1 to explore their interaction." (PMID 37797010, 2023). "Due to their therapeutic value in cancer, the discovery of PIM-1 inhibitors has increasingly attracted much attention in past few years." (PMID 36970406, 2023). "Genetic alterations were found in 6, 8, and 5% of Pim1, Pim2, and Pim3, respectively, in the cancers examined." (PMID 36694243, 2023). "Pim-1 has been shown to regulate cytoskeletal organisation in cancer cells, siRNA mediated Pim-1 knockdown in HUVECs has been shown to attenuate endothelial cell sprouting, but more work is required to elucidate the specific role of Pim-1 in this regard." (PMID 37511341, 2023). "The elevation of CK2 and PIM-1 in cancer cells was shown to involve the suppression of apoptosis, suggesting a protective role for these kinases against cell death." (PMID 36243702, 2022). "PIM1 is an established oncogenic driver, and its inhibition was shown to re-sensitize cancer cells to radiotherapy as well as c-MET and ALK inhibition in NSCLC tumors." (PMID 35360705, 2022). "This is consistent with previous reports from the cancer field demonstrating that PIM1 inhibited apoptosis in tumor cells and enhanced ECM secretion in cancer-associated fibroblasts." (PMID 35167499, 2022). "PIM-1 is closely related to cell cycle regulation, being involved in cell proliferation and survival, and overexpression of PIM-1 is related to the development and progression of various cancers, by increasing cell proliferation and resistance to apoptosis." (PMID 35911521, 2022). "When we further analyzed GRHR-related pathways, we found that GHR was highly expressed in a large number of cancer-related pathways and related to some m6A regulators, as well as PIM1." (PMID 35928449, 2022). "Protein kinases CK2 and PIM-1 are involved in cell proliferation, survival, the cell cycle, and drug resistance, and they are found overexpressed in virtually all types of human cancer, including BC, hence they are considered a potential target of therapy." (PMID 36243702, 2022). "In the breast, miR-486-5p inhibits the epithelial-mesenchymal transition of cancer cells by reducing the expression of PIM1 and PTEN." (PMID 35337095, 2022). "Conversely, PIM1 overexpression in mice leads to cancer development by inhibiting apoptosis, promoting cell proliferation, and inducing of genomic instability." (PMID 36335089, 2022). "IHC profiling showed that PIM-1 was primarily localized in cancer cells and tended to be weakly expressed in untreated CNPC, whereas it was moderately but constitutively expressed in CRPC and apalutamide-treated CNPC." (PMID 34439133, 2021). "A large number of studies link PIM1 activity to a more invasive tumor phenotype and worse prognosis in cancers." (PMID 33946744, 2021). "Our molecular profiling studies revealed increased PIM-1 expression in cancer cells after treatment with apalutamide or GSK690693 and were further increased in tumors from mice treated with combination therapy." (PMID 34439133, 2021).
cancer (continued). "Overexpression of Pim1 has been observed in many cancer types and reported to play a crucial role in tumorigenesis." (PMID 34267653, 2021). "Overexpression of PIM1 appears to influence cancer development in three ways, preventing apoptosis, enhancing cellular proliferation and through promoting genomic instability." (PMID 33933144, 2021). "Introduction of siRNAs for PIM1 re-sensitizes cancer cells to chemotherapy drugs under hypoxia conditions." (PMID 34503111, 2021). "The development and progression of certain cancers due to increased cell proliferation and resistance to apoptosis have been related to the overexpression of Pim1." (PMID 34067108, 2021). "The depletion of PIM1 by RNA interference in mice and cancer cells of the human prostate diminished cell proliferation, survival, and tumorigenicity." (PMID 34503111, 2021). "PIM1 was reported to phosphorylate a variety of cell cycle‐controlling proteins thus enhancing cancer cell proliferation." (PMID 32307917, 2020). "PIM-1 is activated in many types of cancer including prostate, providing a common target for therapy." (PMID 32397108, 2020). "PIM1 is another interphase H3S10 kinase with a documented role in cancer initiation and progression." (PMID 33054831, 2020). "PIM-1 is an oncogene involved in cell cycle progression, cell growth, cell survival and therapy resistance, activated in many types of cancer, and is now considered as a very promising target for cancer therapy." (PMID 32397108, 2020). "As IL-6 impact on cancer cells increased serine-threonine kinase Pim1, over stimulation also led to AR transcriptional reactivity." (PMID 32961987, 2020). "Although dysregulations of the NEK2, PIM1, and PIM3 kinase signaling axes have been implicated in the pathogenesis of several cancers, including those with a neuroendocrine phenotype, their role in the pathogenesis of BP-NENs has not been determined." (PMID 32504181, 2020). "Pim-1 is aberrantly upregulated, in a variety of human cancers and both in vitro and in vivostudies have evidenced the role of Pim-1 in biological activities ofcancerous cells, such proliferation, cell cycle progression, apoptosis,invasion, and glycolysis." (PMID 31359998, 2019). "APubMed literature search was performed to review the currently available data on Pim-1 expression, regulation, and targets; its implicationin different types of cancer and its impact on prognosis is described." (PMID 31359998, 2019). "As Pim-1 possessesoncogenic functions and is over expressed in various kinds of cancer diseases, its inhibition provides a new option in cancer therapy." (PMID 31359998, 2019). "In this review, our objective is to providethe role of the Pim-1 in cancer pathology and the state of the art inthe design and development of PIM inhibitors." (PMID 31359998, 2019). "A number of cancer-associated genes were found, including TGIF1, VEGFA, RUNX1, and PIM1, as well as others." (PMID 29641996, 2018). "To determine the underlying molecular signalling pathways through which depletion of PIM1 elicits anti-proliferation, anti-migration and anti-invasion effects on cancer cells, we examined the effects of PIM1 depletion on EMT in ccRCC cells." (PMID 29472550, 2018). "Increasing evidence indicates that PIM1 is a potential prognostic marker and target for cancer treatment but its precise mechanisms of action remain to be determined in salivary adenoid cystic carcinoma (SACC)." (PMID 29467592, 2018). "PIM-1, a member of a newly defined class of serine/threonine kinases, has been showed to be overexpressed in multiple cancers such as prostate cancer and gastric carcinoma, and possesses oncogenic functions." (PMID 29483938, 2018). "Increasing evidence indicates that PIM1 is a potential target for cancer treatment but its precise mechanisms of action remain to be determined in SACC." (PMID 29467592, 2018).
cancer (continued). "We found that the PIM1 protein was expressed in the nucleus and that its levels were significantly higher in carcinoma tissues than in the surrounding normal tissues." (PMID 29472550, 2018). "p21 is inhibited by PIM-1 in other cancer types, but its expression patterns in HCC are currently unclear." (PMID 29093516, 2017). "PIM-1 is the miR-214 target gene and is overexpressed in many cancer types, including prostate and breast cancers." (PMID 29093516, 2017). "Several studies demonstrated that inhibition of PIM1 activity is an attractive strategy in fighting overexpressing cancers, while distinct structural features of ATP binding pocket make PIM1 an inviting target for the design of selective inhibitors." (PMID 29042609, 2017). "PIM1 is an oncogenic kinase overexpressed in a number of cancers where it correlates with poor prognosis." (PMID 29042609, 2017). "Recently, several microRNAs including miR-33a have been found to directly target PIM1 in different cancer types." (PMID 28947967, 2017). "In this study, we provide the evidence that gankyrin expressed in myeloid cells promote the expansion of cancer-initiating cells through the induction of cancer stem cell markers such as Pim1 and Sox9." (PMID 28160571, 2017). "Approximately 50% of PIM1 transgenic females had malignant carcinoma, with 15% exhibiting disgerminoma." (PMID 28938604, 2017). "According to these findings, we observed that a higher level of PIM1 can protect cancer cells from the inhibitory effects of chemotherapeutic drugs which induce ribosomal stress, such as doxorubicin and cisplatin." (PMID 26993775, 2016). "Our study provides the first evidence that Pim1 regulates c-Kit gene translation and has important implications in hematopoietic stem cell transplantation and cancer treatment." (PMID 28042518, 2016). "Among the biomarker gene pairs, PPP1R13L, EGFR, IL15RA, or PIM1 are acting in the cancer core pathways." (PMID 26916442, 2016). "PIM-1 levels significantly increased in not only cancer tissues but also cancer stroma as reported in a previous study." (PMID 27596051, 2016). "For example, PIM2 modulates mTORC1 activity through phosphorylation of TSC2 in other cancers, while PIM1 phosphorylates PRAS40 thereby relieving its inhibitory effects on mTORC1 with a subsequent increase in mTORC1 activity." (PMID 27120806, 2016). "miR-33a is regarded as a tumor suppressor that targets cancer-associated genes involved in cell proliferation and cell cycle progression, such as CDK6, CCND1 and Pim-1." (PMID 27285759, 2016). "PIM1 is known to enhance cancer cell survival by phosphorylating a number of target genes such as p21waf1, p27Kip1 and Cdc25C." (PMID 25834102, 2015). "In our current study, the novel role of PIM1 in cancer glycolysis sheds light on how PIM1 sustains HCC growth and progression through manipulation of cell metabolism." (PMID 25834102, 2015). "The Pim1 oncogene is involved in multiple human cancers, and enhanced Pim1 expression would benefit vision formation of zebrafish." (PMID 25614096, 2015). "Since hypoxia can drive cancer metastasis, the expression of PIM1 in HCC cell lines in normoxic (20% O2) and hypoxic (1% O2) conditions were analyzed." (PMID 25834102, 2015). "One of them, CX-4945, is considered quite selective for CK2, while the other, TDB, is a dual inhibitor, targeting also PIM-1, another antiapoptotic kinase, which is often overexpressed in cancer cells." (PMID 26558259, 2015). "Pim-1 was a novel target of miR-486-5p determined by luciferase report assay, and ectopic miR-486-5p expression in cancer cells reduced Pim-1 expression." (PMID 25342548, 2014).
cancer (continued). "This study describes a critical role for the oncoprotein Pim-1 in EBV-mediated oncogenesis, as well as provides novel insights into oncogenic kinase-targeted therapeutic intervention of EBV-associated cancers." (PMID 25121590, 2014). "Collectively, these reports suggest that Pim-1’s function is important in the progression of cancer." (PMID 25551195, 2014). "Mechanism analysis showed that PIM-1 contributes to cancer development by phosphorylating multiple target substrates that are tightly related to cells proliferation and anti-apoptosis." (PMID 25040935, 2014). "Among the different kinase targets of KN inhibitors, we select the Pim1 serine/threonine kinase because it is involved in mitotic instability in cancer cells." (PMID 24982612, 2014). "Pim-1 also induces anti-cancer drug resistance by inhibiting the intrinsic mitochondrial apoptosis pathway." (PMID 25121590, 2014). "It stabilizes several cancer-related client proteins including PIM1, AKT, and HIF1A, which are crucial for tumor progression." (PMID 25167922, 2014). "Of them all, pim-1 is considered to be the most useful biomarker for cancer diagnosis and prognosis." (PMID 24116137, 2013). "The 44 kDa PIM-1 mainly localizes to the membrane, whereas the 33 kDa pim-1 localizes to the cytosol and nucleus, indicating that these two isoforms regulate distinct signaling pathways in cancer cells." (PMID 24116137, 2013). "TTP also has multiple important targets, including COX-2, HIF-1α, IL-8, IL-6, IL-8, and VEGF 34,36–40 and the oncogenic Ser/Th kinase Pim-1, which is overexpressed in several cancers and promotes cellular growth and apoptosis resistance 41,42." (PMID 23401122, 2013). "This study represents, to our knowledge, the first spectroscopic and thermodynamic characterization of human kinase Pim-1 and some of its disease relevant mutants found in cancer." (PMID 23755147, 2013). "These conclusions are supported by recent reports showing that Pim-1 synergizes with Myc both to induce advanced prostate carcinoma and to maintain tumorigenicity of the cancer cells." (PMID 23405147, 2013). "Pim-1 is overexpressed in many haematological malignancies and recent studies on Pim family kinases indicate that play important roles also outside of the hematopoietic system, as in the cells of several solid tumors." (PMID 23755147, 2013). "The serine/threonine kinase Pim-1 directs selected signaling events that promote cell growth and survival and is overexpressed in diverse human cancers." (PMID 22413002, 2012). "PIM1 is a serine/threonine kinase frequently over-expressed in cancers of haematological and epithelial origin." (PMID 22140532, 2011). "We here report that lamellarins inhibit several protein kinases relevant to cancer such as cyclin-dependent kinases, dual-specificity tyrosine phosphorylation activated kinase 1A, casein kinase 1, glycogen synthase kinase-3 and PIM-1." (PMID 19172192, 2008). "Over-expression of Pim-1 and Pim-2 in mice promotes the development of lymphomas, and up-regulation of Pim expression has been observed in several human cancers." (PMID 16403219, 2006). "Given its role in cancer, PIM1 is considered a potential target for anticancer drug development." (PMID 41557744, 2026). "In cancer cells, NuMA is phosphorylated by the serine-threonine kinase pim1." (PMID 40681496, 2025). "Notably, several studies have shown that, when Pim1 is blocked by a specific antibody or siRNA in various cancer-cell lines, the phosphorylation of Akt decreases." (PMID 40164682, 2025). "Furthermore, thanks to its role in the regulation of the cell cycle, PIM1 is a critical druggable target in cancer, and interest in this field is increasing, as suggested by several drugs that have been developed against it." (PMID 40943185, 2025).